INS (insulin)
Diseases named in the same sentence as INS in open-access papers (continued):
Sharing a sentence is not in itself a finding about the gene and the disease.
diabetes (continued). "In the remaining subjects, exogenous insulin was still needed for the treatment of diabetes during the two years of the study (insulin maintenance = KPDM+ins, n = 9 patients)." (PMID 25275325, 2014). "This is so because studies have shown that measurement of serum CP provides an accurate assessment of residual beta-cell function and thus has been widely used as a marker of insulin secretion in patients with diabetes." (PMID 25945127, 2014). "Dr. Collip and Dr. Macleod then helped Banting and Best to administer a more refined extract of insulin to Leonard Thompson, a boy suffering from diabetes." (PMID 25574400, 2014). "Individuals with excess hepatic fat or NAFLD are therefore unable to suppress hepatic gluconeogenesis normally in response to insulin, and the continued excessive hepatic glucose production contributes to hyperglycaemia and development of diabetes." (PMID 25159817, 2014). "The changes in endocrine cell mass were reflected in serum hormone levels; hence, while insulin levels decreased in both models of diabetes, glucagon levels increased only in the STZ model of diabetes." (PMID 25101835, 2014). "With the shortage of insulin producing cells in diabetes, pancreas and inslet transplantations have been performed to eliminate the need for insulin injections on a regular basis." (PMID 25120571, 2014). "Over the last decade, there has been considerable interest on the impact of insulin dysfunction and diabetes on Tau pathology." (PMID 24574966, 2014). "CTCF is a general TF that has been reported to mediate the effects of insulin on glucagon expression and therefore is a possible new target for diabetes treatment." (PMID 25399255, 2014). "Plasma insulin level was also measured to estimate degree of disease progression and severity in alloxan induced diabetes model." (PMID 24891878, 2014). "This can be used as a framework for understanding the work of diabetes care in general practice, in particular the task of insulin initiation." (PMID 25361788, 2014). "One well-known example is the wearable artificial endocrine pancreas for diabetes management, which is a close-loop system formed by a wearable glucose monitor and an implanted insulin pump." (PMID 24759283, 2014). "The commercial production of insulin in the 1920 s saw a dramatic decrease in mortality for Type 1 diabetes mellitus patients." (PMID 25426948, 2014). "Limitations in insulin release are also seen in monogenic forms of diabetes such as the group of genes comprising MODY, also with a low overall prevalence at approximately 1% of pediatric diabetes cases." (PMID 24755002, 2014). "It has been reported that, to have a better body image, girls with diabetes often omit insulin injections to avoid weight gain." (PMID 24465941, 2014). "In severely obese children WC better than BMI was investigated as a predictor of fasting blood insulin and in other studies the main predictor of diabetes were BMI and WC." (PMID 24393143, 2014). "In general, the use of insulin to treat type 2 diabetes mellitus during pregnancy is accepted and recommended as safe and effective in achieving normal blood glucose levels." (PMID 24438493, 2014). "In fact, since insulin-induced hypoglycemia is an iatrogenic consequence of treating Type 1 and advanced Type 2 Diabetes Mellitus in the modern world, glucose sensing neurons probably evolved as a defense against starvation." (PMID 25540613, 2014). "It is a target of the synthetic insulin sensitizers – thiazolidinediones - used in the treatment of type 2 diabetes mellitus." (PMID 24524207, 2014). "By contrast, the occurrence of insulin-dependent diabetes mellitus during adolescence in the affected patients indicates an inability of the pancreas to respond to the increase in insulin requirement at puberty." (PMID 25248098, 2014).
diabetes (continued). "Neither gender, nor parameters of disease control (such as HbA1c levels, therapy regimen (oral antidiabetics vs. insulin), duration and complications of diabetes), predicted BMD." (PMID 24721668, 2014). "Combinatorial therapy using insulin with other treatment modalities or insulin use alone is common treatments used for diabetes." (PMID 25197671, 2014). "Transient neonatal diabetes (TNDM) is a rare form of diabetes mellitus characterized by hyperglycemia and low insulin levels within the first year of birth." (PMID 25071830, 2014). "The mean serum glucose levels for the apoE−/− mice with 6 weeks of diabetes and prior to insulin treatment were 364 ± 66 mg/dL for the mice that received the insulin implants and 360 ± 57 mg/dL for the mice that were followed as hyperglycemic controls." (PMID 24829796, 2014). "Type 1 diabetes, which tends to develop in childhood or early adulthood, is responsible for about 10% of cases of diabetes in adults and is treated with injections of insulin." (PMID 25289645, 2014). "Sir Harold Himsworth reported the existence of two types of diabetes in 1935: “insulin sensitive” (type I) and “insulin insensitive” (type II)." (PMID 25574400, 2014). "Improvements in diabetes care and management, with the implementation of newer insulin regimens and analogs, have substantially improved growth in children with T1D by restoring GH-IGF-I axis abnormalities." (PMID 24648838, 2014). "Insulin is always used at a late stage of diabetes when pancreatic β cells are exhausted and most oral anti-diabetic agents fail to adequately control blood glucose." (PMID 24466131, 2014). "While the majority of care for people with T2D takes place in general practice, insulin initiation is commonly deferred to specialist diabetes service, and the majority of Australians with T2D initiate insulin within specialist settings." (PMID 24528528, 2014). "Insulin injections establish glycemic control in diabetes patients, but microvascular and macrovascular complications are still an issue, resulting in lower life expectancy." (PMID 25546435, 2014). "Diabetes is characterized by high blood glucose levels, as results of insufficient insulin due to reduced insulin secretion and/or insulin sensitivity for the body’s required." (PMID 24409188, 2014). "In this study, SR-A−/− nonobese diabetic (NOD) mice showed significant attenuation of insulitis, lower levels of insulin autoantibodies, and suppression of diabetes development compared with NOD mice." (PMID 25343451, 2014). "The other patient was a 61-year-old woman; she had a long duration of diabetes, and her endogenous insulin level was almost depleted." (PMID 24684803, 2014). "Blood glucose monitoring during Ramadan is essential for patients with diabetes who hold fast during Ramadan and more particularly in patients with type 1 diabetes and also in patients with type 2 diabetes who require insulin." (PMID 24559109, 2014). "MicroRNAs (miRNAs) are short (∼22-nt) regulatory RNAs that influence a number of pancreatic events, including the development of pancreatic islets and β cells, insulin secretion, insulin resistance and diabetes." (PMID 25003985, 2014). "As the occurrence of dyslipidemia depends on factors such as insulin action on peripheral tissues and liver, apoprotein production and regulation of lipoprotein lipase, the duration of diabetes seems to play only a minor role in modifying these factors." (PMID 24918095, 2014). "In our study, three subjects received metformin for type 2 diabetes mellitus and two were additionally treated with insulin." (PMID 24692508, 2014). "The aim of this study was to investigate the body composition, the alterations happened by metformin, and their impact on insulin resistance, insulin sensitivity, and metabolic control in adults with newly diagnosed type 2 diabetes mellitus." (PMID 25247153, 2014).
diabetes (continued). "In 127 patients with known and treated diabetes at baseline, insulin (treatment in 49/127 (38.6%) cases) or metformin (treatment in 10/127 (7.9%) cases) had no impact on OS, respectively (insulin, log-rank test p = 0.9687; metformin, log-rank test p = 0.2023)." (PMID 25266049, 2014). "In a similar study, Abutu assessed ß cell function in a group of young insulin treated Nigerians with diabetes." (PMID 25945127, 2014). "These patients were maintained on oral hypoglycaemic tablets, insulin therapy or combination therapy to control their diabetes." (PMID 25018679, 2014). "The Proteobacteria, including the genus Klebsiella, the indicative signature of diabetes, were practically eradicated by insulin from the ileum of the diabetic rats." (PMID 25469509, 2014). "Applying the prespecified exclusion criteria resulted in 4990 cases (41.8% males) of incident insulin users among 79869 individuals initially screened at their first diabetes prescription between January 1, 2001 and December 31, 2008." (PMID 24667573, 2014). "Thirty-nine (19.5%) of patients have been diagnosed with diabetes and were on glucose lowering agents (insulin or oral glucose lowering agent), 28 of them had type 2 diabetes." (PMID 24444396, 2014). "The early introduction of an insulin pump to improve the administration of insulin is likely to delay the development of diabetic retinopathy, which is particularly important for young patients with type 1 diabetes mellitus (T1DM)." (PMID 24688225, 2014). "Insulin allergy is a rare complication of insulin therapy, especially in type 1 diabetes mellitus (T1DM)." (PMID 25548690, 2014). "Intensive insulin therapy is essential in the maintenance of strict glycemic control among insulin requiring patients with diabetes." (PMID 24397956, 2014). "Continuous subcutaneous insulin infusion (CSII) therapy with an external pump and multiple daily injection (MDI) therapy are two of the currently selected methods of insulin treatment for diabetes." (PMID 25187822, 2014). "With different doses of BBE treatment for 3 weeks, the serum insulin level of the diabetes mice improved significantly (P < 0.05)." (PMID 25177729, 2014). "Several drugs, including insulin, tolbutamide, and metformin, are commonly used in the clinic to treat diabetes, and the majority are chemical agents." (PMID 25230123, 2014). "In 2007, only 10% of patients with diabetes (generally patients with type 1 diabetes and some patients with type 2 diabetes treated with insulin) had a consultation with an endocrinologist." (PMID 24555698, 2014). "Insulin requiring diabetes patients (n = 54) attending the 2012 world diabetes day celebration in a Nigerian community were surveyed using a two part questionnaire." (PMID 24397956, 2014). "The well-established actions of GLP-1 as a negative regulator of glucagon and as a positive regulator of insulin and the availabitily of GLP-1RA and DPP-4i provide the opportunity of targeting both main hormones implicated in diabetes pathophysiology." (PMID 25177371, 2014). "For instance, glargine, a long-lasting insulin analogue used for the treatment of diabetes, displays higher mitogenic properties on culture cells in vitro, when compared to insulin." (PMID 24647478, 2014). "Type 1 diabetes mellitus (T1DM) is a common chronic disease in children, characterized by a loss of β cells, which results in defects in insulin secretion and hyperglycemia." (PMID 25364717, 2014). "High BG, polydipsia, polyuria (wetting cages), and reduced insulin are clear signs of diabetes induced by STZ." (PMID 24842144, 2014). "Diabetes mellitus (DM) is a chronic, progressive, incurable metabolic disorder characterized by hyperglycemia due to defective insulin action, insulin secretion or both." (PMID 25230123, 2014). "If lifestyle interventions and oral anti-diabetes drugs (OADs) prove inadequate in controlling glycemic levels, insulin therapy becomes necessary." (PMID 24620742, 2014).
diabetes (continued). "CRC initiation and promotion by diabetes is due to diabetes-induced increase in growth factors (e.g., insulin, IGF-1) and inflammatory adipo/cytokines (e.g., TNFα, IL-6)." (PMID 25375205, 2014). "Resistin was first described as a factor contributing to the development of insulin resistance and diabetes in humans, but debate is still ongoing regarding its role in obesity, insulin sensitivity and the development of T2D." (PMID 25500583, 2014). "To address the significance of hyperglycemia in islet remodeling in diabetes we restored normoglycemia in STZ-diabetic animals by islet transplantation or implantation of an insulin mini-pump." (PMID 25101835, 2014). "Cholesterol concentration remained unchanged during diabetes but increased after insulin replacement." (PMID 25170835, 2014). "Since hyperinsulinemia increases the risk of cardiovascular disease and type 2 diabetes mellitus, our results suggest that the MedDiet may have particular benefits for cardiovascular health in men through its favorable effects on postprandial insulin concentrations." (PMID 25371817, 2014). "The functions of free radicals on the effects of insulin that result in protection against cerebral ischemic insult in diabetes remain undefined." (PMID 25223305, 2014). "Although the pathogenesis of diabetes is complicated by multiple metabolism-related problems, a deterioration of insulin secretion and an aggravation of insulin resistance are 2 central defects in the pathogenesis of diabetes." (PMID 25530810, 2014). "We identified seven preoperative clinical variables (age, duration of diabetes, body mass index, micro and macrovascular complications, use of insulin and stimulated C-peptide) based on our previous reports to be included in the diabetes remission score (DRS)." (PMID 25426451, 2014). "There are several different definitions of the honeymoon period, but they each encompass control of HbA1c with small amounts of insulin, which clearly decreases the influence of the choice of basal insulin on control of diabetes." (PMID 24653838, 2014). "Our research group developed a computer-assisted insulin self-titration system for patients using once daily basal insulin, called the Patient Assisting Net-based Diabetes Insulin Titration (PANDIT) system." (PMID 25340869, 2014). "As far as the method of compensation for the sugar diabetes is concerned, 43.1% have followed a treatment with insulin and 56.9% have used oral antidiabetics, providing them with a low metabolic balancing." (PMID 25870688, 2014). "There was a slight over-representation of males and the prevalence of CF-related diabetes was lower than reported in the literature, as it was stringently defined based on the need for insulin therapy." (PMID 24586701, 2014). "Impaired endothelial function has been described in very early stages of diabetes mellitus and hyperglycemia, and decreased insulin-sensitivity, as well as increased oxidative stress, have been proposed as possible contributors." (PMID 25047034, 2014). "The number of clinical visits was related with the intensity of the insulin therapeutic regimen, which reinforced the idea that regular clinic attendance is an important component of intensive diabetes management." (PMID 24920963, 2014). "ATP-sensitive K+ (KATP) channel blockers are prescribed to individuals who are in the diabetes-aged population and who display impaired glucose-induced insulin release." (PMID 25505577, 2014). "Diabetes and insulin replacement affect the composition of the gut microbiota in different, gut region-specific manners." (PMID 25469509, 2014). "More south Asians were treated with insulin or a combination of insulin and tablets, compared with white Europeans (18.3% vs. 13.2%), while more white Europeans controlled their diabetes solely through diet (28.9% vs. 11.8%)." (PMID 24902492, 2014).
diabetes (continued). "Previous studies have found several risk factors of DR incidence in type 2 diabetes patients, including hypertension, hyperglycemia, long diabetes duration, smoking, insulin therapy, and obesity." (PMID 25402474, 2014). "Insulin, as well as other oral and injectable diabetes medications combined with an exercise program, are the most common therapies prescribed to reduce blood glucose levels in diabetic patients." (PMID 24587200, 2014). "Diabetes mellitus (DM) is a group of metabolic diseases characterized by hyperglycemia, which results from defects in insulin secretion, insulin activity or both." (PMID 25421534, 2014). "As diabetes is also a marker of long-standing insulin resistance - with chronically high insulin levels and high fasting blood glucose - it is critical that metabolic syndromes have also been associated with BC risk." (PMID 24903828, 2014). "Type 1 diabetes, type 2 diabetes requiring insulin or oral hypoglycaemic drugs, diet controlled diabetes." (PMID 24433371, 2014). "Patients with diabetes underwent moderate or semi-tight glycemic control, using continuous intravenous insulin infusion." (PMID 25478539, 2014). "This consideration is of importance particularly if the intention is to encourage third party websites to link to AIDA online and the Diabetes/Insulin Tutorial." (PMID 24511312, 2014). "Sodium vanadate was applied in diabetes therapy 22 years before the first use of insulin to treat diabetes in human beings." (PMID 25667581, 2014). "Missing data regarding oral antidiabetic treatment of newly diagnosed cystic fibrosis related diabetes are an important reason to recommend insulin treatment." (PMID 24620855, 2014). "In patients with insulin requiring type 2 diabetes mellitus, perilipin 1 mRNA and protein levels were reduced when the insulin was withheld and patients were hyperglycemic compared to when they were on insulin and euglycemic." (PMID 25118138, 2014). "This cytokine therefore represents a promising target to influence insulin resistant states in diabetes." (PMID 25025664, 2014). "Previously, PI3K, as an important molecule in insulin signaling pathway, had been found to play a vital role in diabetes." (PMID 25183970, 2014). "Ketoacidosis was managed by insulin and insulin daily requirement began to dwindle after one month, until its complete withdrawal at 8 weeks, when partial remission was reached." (PMID 25332771, 2014). "Self monitoring of blood glucose is well-established as an important component of diabetes management for insulin-treated patients and has also been found to be important in some studies of non-insulin dependent patients." (PMID 25100190, 2014). "The mRNA coding for PPARγ increased in intra-abdominal WAT during diabetes and decreased during insulin replacement, that is the exact opposite of adipogenesis." (PMID 25170835, 2014). "It was reported that inhibitors of these enzymes would have a dual protective role in diabetes, by minimizing beta-cell dysfunction and by maintaining insulin secretion through enhancing endogenous arachidonic acid levels." (PMID 25396726, 2014). "Insulin resistance is a condition in which normal amounts of insulin are inadequate to produce normal insulin response from fat, muscles and liver cells; it is a state that precedes type 2 diabetes mellitus." (PMID 25713604, 2014). "WC was significantly associated with age, income and management of diabetes by OHA and insulin (p < 0.05)." (PMID 25113234, 2014). "Regarding treatment, 92.6% reported some type of diabetes treatment: 60.4% engaging in dietary modifications, physical activity, and drug use, and 19.3% using only oral hypoglycemic agents or insulin." (PMID 25255096, 2014). "In some cases, e.g. fibrillar deposits of insulin, the problems are generated in the processes of production and purification of protein and in the pump devices or injectable preparations for diabetics." (PMID 24572069, 2014).